HGH1 (HGH1 cochaperone)
Description:
Co-chaperone involved in the folding of nascent eukaryotic elongation factor eEF2, an essential component of the translation machinery. Recognizes a non-native conformation in the central domain of eEF2 and recruits the chaperonin-containing T-complex (TRiC) to the C-terminal region of the nascent polypeptide, preventing unproductive interactions and promoting efficient folding of the N-terminal GTPase domain. May also assist in eEF2 maturation by recruiting the molecular chaperone Hsp90.
Synonyms: C8orf30A; C8orf30B; FAM203A; FAM203B; FLJ40907; LOC51236; Brp16; BRP16L
Tractability: PROTAC: ubiquitination databases record sites on it; its protein half-life has been measured.
Gene: Protein-coding gene on chromosome 8 (144,137,774 to 144,140,851, forward strand). Ensembl gene ENSG00000235173.
Subcellular location: Cytoplasm
Subcellular location (Human Protein Atlas): Cytosol; Nuclear bodies; Nucleoplasm
Gene Ontology:
Molecular function: protein binding
Cellular component: cytoplasm
Genetic constraint (gnomAD): Loss-of-function variants: 31 observed, 29.04 expected, observed/expected ratio (o/e) 1.07, 90% interval 0.8 to 1.44. The synonymous counts are far from expectation, so gnomAD's model fits this gene poorly and the ratio says little. Missense variants: 618 observed, 455.21 expected, observed/expected ratio (o/e) 1.36, 90% interval 1.27 to 1.45. Synonymous variants: 284 observed, 216.98 expected, observed/expected ratio (o/e) 1.31, 90% interval 1.19 to 1.44.
Homologues: Orthologues: chimpanzee HGH1 (99% identical), macaque HGH1 (97% identical), dog HGH1 (87% identical), pig HGH1 (84% identical), guinea pig HGH1 (81% identical), mouse Hgh1 (77% identical), rat Hgh1 (76% identical), rabbit HGH1 (71% identical), zebrafish hgh1 (52% identical), tropical clawed frog hgh1 (49% identical), Drosophila melanogaster CG6073 (33% identical), Caenorhabditis elegans Y54H5A.2 (22% identical).
Diseases named in the same sentence as HGH1 in open-access papers:
HGH1 is named in the same sentence as 7 diseases in open-access papers, as found by Europe PMC text mining. Sharing a sentence is not in itself a finding about the gene and the disease. The quoted sentences say what the papers report.
breast carcinoma (4 papers, 2022 to 2025). "In breast cancer, NSUN2 promotes tumorigenesis by modulating the expression of HGH1 and stabilizing its mRNA, suggesting that HGH1 could be a potential therapeutic target." (PMID 41256854, 2025).
colorectal cancer (2 papers, 2023 to 2025). A primary or metastatic malignant neoplasm that affects the colon or rectum. "FAM203B (HGH1) mediates colorectal cancer cell proliferation, migration, EMT, and stemness." (PMID 40611658, 2025). "LncRNA CASC21 induced HGH1 expression by recruiting POU5F1B to the HGH1 promoter in the nucleus and sponging miR-485-5p in the cytoplasm, thereby facilitating colorectal cancer cell proliferation, migration and stemness." (PMID 36672487, 2023).
glioblastoma (1 paper, 2013). The most malignant astrocytic tumor (WHO grade IV). "Similar results were obtained with the related rodent parvovirus strain hgH1-PV after infection of the human glioblastoma cell line NCH149, suggesting that vesicular egress of progeny virions is a general feature of rodent PVs." (PMID 24068925, 2013).
cancer (2 papers, 2022 to 2025). A tumor composed of atypical neoplastic, often pleomorphic cells that invade other tissues. "Based on the transcriptomic data of TCGA pan-cancer cohorts, the expression of RRP1B, RRP1, MAZ, DUS1L, and HGH1 was identified to correlate positively with the expression of SLC19A1 in 40 types of cancers." (PMID 40149548, 2025).
HGH1 also shares sentences with these, for which no sentence is quoted: Tumor (2 papers); infection (1); neurodevelopmental disorder (1).